GSTO1 (glutathione S-transferase omega 1)
Diseases named in the same sentence as GSTO1 in open-access papers (continued):
Sharing a sentence is not in itself a finding about the gene and the disease.
inflammation (1 paper, 2022). Aberrant reaction of the microcirculation characterized by movement of fluid and leukocytes from the blood into extravascular tissues. "Our previous study found that Tet1 deletion enhanced HDM-induced lung inflammation in mice, and that it was linked to transcriptomic changes in proinflammatory molecules (Il33) and detoxification enzymes (Gsto1 and Aldh1a1) in total lung RNA." (PMID 35627266, 2022).
GSTO1 also shares sentences with these, for which no sentence is quoted: hepatocellular carcinoma (3 papers); cholangiocarcinoma (2); melanoma (2); non-small cell lung carcinoma (2); thyroid nodule (2); type 2 diabetes mellitus (2); amyotrophic lateral sclerosis (1); Barrett esophagus (1); benign prostatic hyperplasia (1); cardiovascular disease (1); colorectal tumor (1); coronary heart disease (1); epilepsy (1); esophageal adenocarcinoma (1); esophageal cancer (1); germ cell tumor (1); head and neck cancer (1); kidney cancer (1); leukemia (1); mantle cell lymphoma (1); neurological disorders (1); nicotine dependence (1); oesophageal cancers (1); papillary carcinoma (1); polyp (1); renal cell carcinoma (1); Renal cyst (1); testicular cancer (1); thyroid (1).